RTKN2 (rhotekin 2)
Description:
May play an important role in lymphopoiesis.
Synonyms: PLEKHK1; Em:AC024597.2; bA531F24.1; FLJ39352
Tractability: Antibody: its Gene Ontology location is reachable by antibodies, with medium confidence. PROTAC: ubiquitination databases record sites on it.
Gene: Protein-coding gene on chromosome 10 (62,183,035 to 62,268,844, reverse strand). Ensembl gene ENSG00000182010.
Subcellular location (Human Protein Atlas): Nucleoplasm; Mitochondria
Gene Ontology:
Biological process: adaptive immune response; intracellular signal transduction; hemopoiesis; positive regulation of cell population proliferation; signal transduction
Cellular component: cytoplasm; nucleus
Genetic constraint (gnomAD): Loss-of-function variants: 35 observed, 32.07 expected, observed/expected ratio (o/e) 1.09, 90% interval 0.83 to 1.45. The upper end of that interval is the gene's LOEUF score, 1.45, which puts it in group 5 of 6, group 1 being the genes least tolerant of losing a copy. Missense variants: 420 observed, 407.38 expected, observed/expected ratio (o/e) 1.03, 90% interval 0.95 to 1.12. Synonymous variants: 132 observed, 142.29 expected, observed/expected ratio (o/e) 0.93, 90% interval 0.8 to 1.07.
Gene-disease validity (ClinGen):
ClinGen rates the evidence that RTKN2 causes each of these diseases.
dilated cardiomyopathy (autosomal recessive): No Known Disease Relationship. Cardiomyopathy which is characterized by dilation and contractile dysfunction of the left and right ventricles.
Homologues: Orthologues: chimpanzee RTKN2 (99% identical), macaque RTKN2 (97% identical), pig RTKN2 (87% identical), rabbit RTKN2 (86% identical), dog RTKN2 (85% identical), guinea pig RTKN2 (75% identical), mouse Rtkn2 (72% identical), rat Rtkn2 (71% identical), tropical clawed frog rtkn2 (58% identical), zebrafish rtkn2 (46% identical). Paralogues in human: RTKN (35% identical), ANLN (15% identical).
Diseases named in the same sentence as RTKN2 in open-access papers:
RTKN2 is named in the same sentence as 30 diseases in open-access papers, as found by Europe PMC text mining. Sharing a sentence is not in itself a finding about the gene and the disease. The quoted sentences say what the papers report.
hepatocellular carcinoma (13 papers, 2018 to 2025). A malignant tumor that arises from hepatocytes. "Analogously, hsa_circRNA_104348 has been implicated in the progression of hepatocellular carcinoma by modulating the miR-187-3p/RTKN2 axis and activating the Wnt/β-catenin pathway." (PMID 38806577, 2024). "In hepatocellular carcinoma, hsa_circ_104348 facilitates metastasis via the miR-187-3p/Rhotekin 2 (RTKN2) axis; circRNA-SORE induces resistance to sorafenib through miR-103a-2-5p/miR-660-3p; and hsa_circ_0004018 exerts tumor-promoting functions." (PMID 41050070, 2025). "For example, hsa_circRNA_104,348 promotes hepatocellular carcinoma progression by modulating miR-187–3p/RTKN2 axis and activating Wnt/β-catenin pathway." (PMID 39293372, 2024). "Hsa_circRNA_104348, for example, is capable of targeting the miR-187-3p/rhotekin 2 (RTKN2) axis and driving the activation of Wnt/β-catenin signaling in a manner conducive to hepatocellular carcinoma progression." (PMID 38440120, 2024). "RTKN2 was upregulated in hepatocellular carcinoma, and enhanced expression of RTKN2 suppressed cell apoptosis and facilitated the migration and invasion." (PMID 38155217, 2023). "Huang's research showed hsa_circRNA_104348 promotes hepatocellular carcinoma progression through modulating miR-187-3p/RTKN2 axis and activating Wnt/β-catenin pathway." (PMID 34899908, 2021). "The flow cytometry data and Hoechst 33258 indicated that the silencing of RTKN2 resulted in notable induction of apoptosis, which was in keeping with previous studies on hepatocellular carcinoma, bladder cancer, leukemic, and colon cancer." (PMID 30389712, 2018). "CircRNA 104348 modulates the miR-187-3p/RTKN2 axis to promote hepatocellular carcinoma progression." (PMID 35453537, 2022). "For example, circ_103809 targets miR-620 to suppress proliferation and invasion in HCC, and hsa_circ_104348 modulates the miR-187-3p/RTKN2 axis in hepatocellular carcinoma progression." (PMID 38383334, 2024).
lung carcinoma (5 papers, 2018 to 2023). "In this study, bioinformatic analysis indicated that RTKN2 was expressed at low levels in lung cancer cells, which was further confirmed by qPCR and western blot assays." (PMID 36952123, 2023). "Conversely, overexpression of RTKN2 blocked the glycolysis, cell growth, invasion and migration of lung cancer cells via the regulation of the NF‐κB pathway." (PMID 38155217, 2023). "SPP1, AGER, and RTKN2 regulate the lung cancer-related pathways such as VEGF (vascular endothelial growth factor) signaling pathway and NF-kappaB." (PMID 30453959, 2018). "Nevertheless, we suggested that BIRC5, FGF2, RTKN2 and SLIT3 may be important for lung cancer; but experiment verification should be performed in future." (PMID 32299382, 2020). "Involvement of highly significant DEGs including SLCO1A2, OLFM4, RTKN2, CYP1A1, and MUC5AC plays a key role in rheumatoid arthritis development.Highly significant DEGs including OLFM4, RTKN2, CYP1A1, MUC5AC, CYP2A6, PCK1, and PITX1 have been reported to encourage the development of lung cancer." (PMID 38137330, 2023).
bladder cancer (3 papers, 2018 to 2024). "Rhotekin 2 (RTKN2) is a protein which is expressed in various tissues, but it has been reported that RTKN2 is upregulated in some cancers such as ovarian cancer, bladder cancer and HCC." (PMID 37546393, 2023).
colon cancer (3 papers, 2018 to 2024). "RTKN2 is a new effector protein of Rho GTPase, and has been indicated to be a tumor inhibitor in colon cancer." (PMID 38155217, 2023).
rheumatoid arthritis (3 papers, 2012 to 2023). A chronic, systemic autoimmune disorder characterized by inflammation in the synovial membranes and articular surfaces. "Genetic variants in rhotekin 2 have been associated with rheumatoid arthritis (RA) and activation of the NF-κB pathway in Japanese." (PMID 26503507, 2015). "Association analysis of NFKBIE and RTKN2 with rheumatoid arthritis." (PMID 23028356, 2012).
autoimmune disease (2 papers, 2012 to 2023). A disorder resulting from loss of function or tissue destruction of an organ or multiple organs, arising from humoral or cellular immune responses of the individual to their own tissue constituents. "The RTKN2 gene is expressed in lymphocytes, induces an NF-kB-dependent hold on apoptosis that can change counts and function of available immune cells, and has been implicated in autoimmune disease." (PMID 38288162, 2023). "As the majority of autoimmune disease loci have been implicated as eQTL, we speculated that variants in the NFKBIE and RTKN2 loci would influence gene function by regulating gene expression, in addition to changing the amino acid sequences." (PMID 23028356, 2012).
breast carcinoma (2 papers, 2021 to 2023). "However, other molecular mechanisms of action of RTKN2 in breast cancer remain unknown." (PMID 38155217, 2023).
gastric cancer (2 papers, 2011 to 2024). A primary or metastatic malignant neoplasm involving the stomach. "Rhotekin 2 (RTKN2) is recognized as an oncogene in locally advanced gastric cancer (GC)." (PMID 39388011, 2024).
meningioma (2 papers, 2016). A generally slow growing tumor attached to the dura mater. "Among genes that were higher expressed in meningiomas from females were rhotekin 2 (RTKN2), neuritin 1 (NRN1), small nucleolar RNA, C/D box 114–26 (SNORD114-26), and leucine rich adaptor protein 1-like (LURAP1L)." (PMID 27096627, 2016).
osteosarcoma (2 papers, 2018 to 2023). A usually aggressive malignant bone-forming mesenchymal neoplasm, predominantly affecting adolescents and young adults. "We next detected the levels of RTKN2 in two human osteosarcoma cell lines and a normal osteoblast cell line by real-time PCR and western blot." (PMID 30389712, 2018). "RTKN2 silencing on cell proliferation of human osteosarcoma cells, and the potential mechanism was examined." (PMID 30389712, 2018). "The expression level of RTKN2 was markedly higher in U2OS cells, so we selected U2OS cells to investigate the function of RTKN2 in human osteosarcoma." (PMID 30389712, 2018). "In this study, RTKN2 silencing induced cell cycle arrest in G1 phase in the human osteosarcoma U2OS cells, which indicated that the inhibition of proliferation in human osteosarcoma cells was associated with the cell cycle arrest." (PMID 30389712, 2018). "In the present study, we found that the level of Rhotekin 2 (RTKN2) was up-regulated in osteosarcoma tissues and cell lines." (PMID 30389712, 2018). "We analyzed the mRNA and protein levels of RTKN2, and found that the level of RTKN2 was up-regulated in osteosarcoma tissues and human osteosarcoma cells." (PMID 30389712, 2018). "A colony formation assay was carried out to determine the colony forming capacity of osteosarcoma cells after the knockdown of RTKN2." (PMID 30389712, 2018). "Compared with the normal osteoblast cell line, RTKN2 overexpression was detected at both the mRNA and protein levels in osteosarcoma cell lines." (PMID 30389712, 2018). "Silencing of RTKN2 inhibited proliferation of human osteosarcoma cells, arrested the cell cycle in G1 phase, and induced human osteosarcoma cells apoptosis." (PMID 30389712, 2018). "A 6-day growth curve analysis showed that the RTKN2 silencing significantly inhibited the proliferation of human osteosarcoma U2OS cells." (PMID 30389712, 2018). "Functional study by knockdown of RTKN2 helped us illustrate the important role of RTKN2 in human osteosarcoma that RTKN2 silencing resulted in suppressed growth of human osteosarcoma cells and impaired colony formation ability of human osteosarcoma cell." (PMID 30389712, 2018). "This indicated the presence of correlation between RTKN2, cell cycle progression, and the regulation of DNA replication in human osteosarcoma cells." (PMID 30389712, 2018). "The present study investigated the expression of RTKN2 in osteosarcoma tissues and human osteosarcoma cell lines." (PMID 30389712, 2018). "In conclusion, our study showed that RTKN2 was overexpressed in human osteosarcoma." (PMID 30389712, 2018). "However, silencing of RTKN2 induces apoptosis of human osteosarcoma U2OS cells, with featured typical characteristics of apoptosis, including the condensation of chromatin, the shrinkage of nuclei, and the appearance of a few apoptotic bodies." (PMID 30389712, 2018). "In addition, silencing of RTKN2 of human osteosarcoma cell lines U2OS, inhibited proliferation, and induced G1 phase cell cycle arrest via reducing the level of the cyclin-dependent kinase 2 (CDK2)." (PMID 30389712, 2018). "In this study, we primarily found that RTKN2 was critical for osteosarcoma cell survival." (PMID 30389712, 2018). "However, up to now, the biological functions of RTKN2 in human osteosarcoma remain to be unclear." (PMID 30389712, 2018). "The results showed that RTKN2 may play an important role in osteosarcoma." (PMID 30389712, 2018).
Allergy (1 paper, 2019). An allergy is an immune response or reaction to substances that are usually not harmful. "The up-regulated genes have been previously associated with asthma; hyper-reactivity and allergy (CCR2, HRH2, PTEN); lung development and apoptosis (CHRNA7, RTKN2); and immune function (GIMAP4, GIMAP7, KLRC3 and CD99)." (PMID 30971730, 2019).
Alzheimer disease (1 paper, 2024). A progressive, neurodegenerative disease characterized by loss of function and death of nerve cells in several areas of the brain leading to loss of cognitive function such as memory and language. "The overlapping of the omic levels investigated here with data from a public FP Quantitative Trait Loci (QTL) database revealed novel candidate genes for understanding repetitive behaviours, such as RTKN2, associated with Alzheimer’s disease in humans." (PMID 39702044, 2024). "In the brain, RTKN2 participates in the downstream transcriptional regulation of the amyloid precursor protein, an important player in Alzheimer’s disease." (PMID 39702044, 2024).
disc degeneration (1 paper, 2019). "Interestingly, we identified three hypermethylated genes in the advanced stage of disc degeneration (CARD14, EFHD2 and RTKN2) that are involved in the regulation of the NF-κB pathway." (PMID 31513634, 2019).
Graves disease (1 paper, 2012). Graves' disease is an autoimmune disorder that leads to overactivity of the thyroid gland (hyperthyroidism).It is caused by an abnormal immune system response that causes the thyroid gland to produce too much thyroid hormones. "As the association of RTKN2 locus was also implicated in Graves' disease in a Han Chinese population, the association in RTKN2 locus may be unique to Asian populations." (PMID 23028356, 2012).
head and neck cancer (1 paper, 2022). A primary or metastatic malignant neoplasm affecting the head and neck. "Additionally, we identified a single variant in our head and neck cancer-specific analysis, rs12253181 (RTKN2, OR [95% CI] = 1.99 [1.67, 2.37])." (PMID 36199081, 2022).
lung adenocarcinoma (1 paper, 2023). A carcinoma that arises from the lung and is characterized by the presence of malignant glandular epithelial cells. "The GEPIA online database was used to analyse abnormally expressed genes in lung adenocarcinoma and RTKN2 expression in various cancers." (PMID 36952123, 2023).
vitiligo (1 paper, 2025). Generalized well circumscribed patches of leukoderma that are generally distributed over symmetric body locations and is due to autoimmune destruction of melanocytes. "Here, we identified 13 cell subsets and found that, compared with those in healthy individuals, Treg cells in progressive vitiligo patients are more abundant and express genes such as RTKN2, IKZF2, IL2RA, and STAM." (PMID 41438750, 2025).
cancer (7 papers, 2011 to 2023). A tumor composed of atypical neoplastic, often pleomorphic cells that invade other tissues. "RTKN2 is a new effector protein of Rho GTPase family, and has been identified to serve as a specific role in several cancers." (PMID 38155217, 2023). "Abnormally expressed RTKN2 was demonstrated to modulate the development of various cancers." (PMID 36952123, 2023). "Dysfunction of RTKN2 has been reported to play an important role in numerous types of cancer." (PMID 30389712, 2018). "The involvement of RTKN2 in several types of cancer has been reported." (PMID 30389712, 2018). "Thus, our results showed that RTKN2 is a cancer-promoting factor in BC." (PMID 38155217, 2023). "RTKN2, NFIX, PTX3, BMP2 and LOXL2 of the ceRNA network play an important role in cancer progression." (PMID 34394080, 2021). "RTKN2 inhibited the malignant behaviour and glycolysis of LUAD cells by blocking the NF-κB signalling pathway, implying that RTKN2 could be a cancer suppressor in LUAD progression." (PMID 36952123, 2023).
tumor (7 papers, 2020 to 2025). "Hsa_circRNA_104348 is upregulated in HCC tumor cells and promotes tumor progression and invasion via the Wnt/beta catenin and miR-187–3p/RTKN2 pathways, leading to a poor response to ICIs." (PMID 36230554, 2022). "The expression of RTKN2 was significantly up-regulated in tumor tissues compared with control (P < 0.01)." (PMID 33311442, 2020). "Our data indicated that RTKN2 silencing blocked tumor progression in vivo." (PMID 38155217, 2023). "All these data confirmed that RTKN2 knockdown played a tumor suppressor in BC cell progression." (PMID 38155217, 2023). "In addition, expression of protein RTKN2 was detected in five pairs of tumor tissues or normal tissues." (PMID 33311442, 2020). "Additionally, we also demonstrated that RTKN2 knockdown restrained tumor growth in vivo." (PMID 38155217, 2023). "High expression of CD4_C12-CTLA4 (tumor regulatory T cell, Tumor-Treg) markers, such as CCR8, RTKN2, and FOXP3, was observed in C1." (PMID 33584715, 2020). "Similarly, RTKN2 exacerbated the tumor development by regulating MM92 and MMP9 expression in non-small cell lung cancer." (PMID 38155217, 2023).
RTKN2 also shares sentences with these, for which no sentence is quoted: ovarian carcinoma (2 papers); Alzheimer ́s disease (1); asthma (1); cervical cancer (1); clear cell renal cell carcinoma (1); frontotemporal dementia (1); hypothyroidism (1); idiopathic interstitial pneumonia (1); lung fibrosis (1); lupus (1); Wilms tumor (1).